NANOGP8 (Nanog homeobox retrogene P8)
Diseases named in the same sentence as NANOGP8 in open-access papers (continued):
Sharing a sentence is not in itself a finding about the gene and the disease.
tumor (8 papers, 2015 to 2024). "To understand more about NANOGP8 association with tumor cell properties such as cell invasion, proliferation and self-renewal capacities, we performed transwell Boyden chamber assay, MTT experiment and clonogenic assay." (PMID 29689047, 2018). "Our study showed a statistically significant decrease of all surface markers and NANOGP8 immediately after tumor ablation." (PMID 39473666, 2024). "Taken together, our present work demonstrates that transgenic overexpression of NanogP8 in the mouse prostate is insufficient to initiate tumorigenesis but weakly promotes tumor development in the Hi-Myc mouse model." (PMID 28881767, 2017). "As a result, even a macroscopically undetectable tumor could release a significant amount of NANOGP8-enriched EVs." (PMID 39473666, 2024). "The exosomal DNA of NANOGP8 gene may have a promoter with differential sequences that can be activated depending on the tumor microenvironment and the availability of oncogenic TFs." (PMID 36696426, 2023). "We believe that the differential promoter sequences of exosomal DNA, combined with the microenvironment of a tumor, and the availability of oncogenic transcription factors, may have an essential role in NANOGP8 expression." (PMID 36696426, 2023). "In the present study, we have also observed that prostate-specific NanogP8 overexpression slightly accelerates the tumorigenic process in the VPs of Hi-Myc mice, suggesting that Nanog might cooperate with Myc in promoting tumor development." (PMID 28881767, 2017). "We initially hypothesized that similar to Oct4 and Sox2 overexpression, NanogP8 expression in epithelial cells might be able to trigger spontaneous tumor formation in mice." (PMID 28881767, 2017). "We first examined NANOG1−/− and NANOGP8−/− cell proliferation in a monolayer to examine whether NANOG1 and NANOGP8 were involved in these well-known tumor cell properties." (PMID 26087476, 2015). "Moreover, we assessed the potential correlations between preoperative NANOGP8 and tumor dimensions at the moment of diagnosis (p = 0.07, Spearman r = -0.3699) and between NANOGP8 and KPS at T1, T2, and T3, yet no statistically significant results have been obtained." (PMID 39473666, 2024). "There were patients with MRI-proven recurrence with no detectable bands of NANOGP8 protein at T3 (e.g., G14), whereas there were subjects with no macroscopically apparent tumor having a high level of NANOGP8 (e.g., G15)." (PMID 39473666, 2024). "Along with the finding that the centrosomal localization of NANOG/NANOGP8 was detected in various tumor and non-tumor cell types, these results provide the first evidence suggesting a common centrosome-specific role of NANOG." (PMID 32168958, 2020). "To address the key unanswered question whether tissue-specific overexpression of NanogP8 is sufficient to promote tumor development in vivo, we generated a NanogP8 transgenic mouse model, in which the ARR2PB promoter was used to drive NanogP8 cDNA." (PMID 28881767, 2017). "Results from the present study indicate that even targeted overexpression of NanogP8 specifically in the luminal cells of the mouse prostate does not, by itself, promote tumor development." (PMID 28881767, 2017). "We subcutaneously injected 2 × 106NANOG1-knockout cells, NANOGP8-knockout cells, or parental cells into non-obese diabetic/severe combined immunodeficient (NOD-SCID) mice to determine whether NANOG depletion influences tumor development in vivo." (PMID 26087476, 2015).
infection (1 paper, 2018). The state of being infected such as from the introduction of a foreign agent such as serum, vaccine, antigenic substance or organism. "A stable cell line was established with infection of lentivirus containing NANOGP8." (PMID 29689047, 2018).
NANOGP8 also shares sentences with these, for which no sentence is quoted: brain tumor (1 paper); embryonal carcinoma (1); hepatocellular carcinoma (1); Parkinson disease (1); prostate (1).